MIRLET7F1 (microRNA let-7f-1)
Synonyms: hsa-let-7f-1; LET7F1; MIRNLET7F1; let-7f-1
Gene: MicroRNA gene on chromosome 9 (94,176,347 to 94,176,433, forward strand). Ensembl gene ENSG00000199072.
Gene Ontology:
Biological process: miRNA-mediated post-transcriptional gene silencing
Cellular component: RISC complex
Homologues: Orthologues: chimpanzee ptr-let-7f-1 (100% identical), macaque MIRLET7F1 (100% identical), pig ssc-let-7f-2 (100% identical), rabbit MIRLET7F1 (100% identical), guinea pig MIRLET7F1 (99% identical), tropical clawed frog xtr-mir-98 (76% identical). Paralogues in human: MIR98 (74% identical), MIRLET7F2 (69% identical), MIRLET7G (68% identical), MIRLET7A1 (66% identical), MIRLET7A3 (64% identical), MIRLET7D (63% identical), MIRLET7E (59% identical), MIRLET7I (59% identical), MIRLET7C (57% identical), MIRLET7A2 (56% identical).
Diseases named in the same sentence as MIRLET7F1 in open-access papers:
MIRLET7F1 is named in the same sentence as 3 diseases in open-access papers, as found by Europe PMC text mining. Sharing a sentence is not in itself a finding about the gene and the disease. The quoted sentences say what the papers report.
emphysema (1 paper, 2024). "In the present study, we established that the Mirlet7 family members encoded by the Mirlet7b/Mirlet7c2 and Mirlet7a1/Mirlet7f1/Mirlet7d clusters are downregulated in T cells from lungs of emphysema patients and emphysematous mice that were exposed to CS or nCB." (PMID 38722677, 2024). "Here, we show that overall expression of the Mirlet7 clusters, Mirlet7b/Mirlet7c2 and Mirlet7a1/Mirlet7f1/Mirlet7d, are reduced in the lungs and T cells of smokers with emphysema as well as in mice with cigarette smoke (CS)- or nCB-elicited emphysema." (PMID 38722677, 2024). "Next, we elucidated Mirlet7b/Mirlet7c2 and Mirlet7a1/Mirlet7f1/Mirlet7d cluster expression (herein referred to as Mirlet7bc2 and Mirlet7afd, respectively) in murine models of CS- or nCB-induced emphysema, respectively." (PMID 38722677, 2024). "Consistently, the analogous murine Mirlet7b/Mirlet7c2 and Mirlet7a1/Mirlet7f1/Mirlet7d clusters, respectively, were similarly downregulated in pre-clinical emphysema models." (PMID 38722677, 2024). "We did not ascertain whether deletion of Mirlet7a1/Mirlet7f1/Mirlet7d cluster is an equally or more effective modulator of experimentally induced emphysema." (PMID 38722677, 2024).
cancer (1 paper, 2018). A tumor composed of atypical neoplastic, often pleomorphic cells that invade other tissues. "MIRLET7A1, MIRLET7F1, MIRLET7D are microRNA genes which are involved in cancer and DNA damage response pathways." (PMID 30386687, 2018).
MIRLET7F1 also shares sentences with these, for which no sentence is quoted: teratospermia (1 paper).